PDCD5 (programmed cell death 5)
Diseases named in the same sentence as PDCD5 in open-access papers (continued):
Sharing a sentence is not in itself a finding about the gene and the disease.
cancer (17 papers, 2005 to 2023). A tumor composed of atypical neoplastic, often pleomorphic cells that invade other tissues. "PDCD5, a highly conserved protein, was first identified as an apoptosis‐promoting signal in many diseases, including cancers." (PMID 36578176, 2023). "Pdcd5 plays an important role in the process of cell apoptosis, and it was downregulated in many cancers." (PMID 36875640, 2023). "The PDCD5 gene regulates cell proliferation, cell cycle progression, and apoptosis in bovine cancer cells (A431)." (PMID 36230283, 2022). "It is noteworthy that the implication of PDCD5/HDAC3/miR-195-5p/SGK1 axis in RCC has been rarely studied through their respective interaction which has been briefly mentioned in other cancers." (PMID 36266728, 2022). "The decreased expression of PDCD5 has been detected in many human tumors, and restoration of PDCD5 with recombinant protein can significantly sensitize different cancer cells to chemotherapies." (PMID 25178696, 2015). "Previously, PDCD5 has been shown to suppress growth of multiple types of cancer cells by promoting apoptosis." (PMID 22253891, 2012). "However, human PDCD5 is essential for inflammation and cancer through regulating apoptosis." (PMID 31281315, 2019). "Low expression levels of the programmed cell death 5 (PDCD5) gene have been reported in numerous human cancers, however, PDCD5 expression has not been investigated in hepatic cancer." (PMID 25436001, 2015).
infection (1 paper, 2025). The state of being infected such as from the introduction of a foreign agent such as serum, vaccine, antigenic substance or organism. "We then investigated the impact of PDCD5 on CD8+ T cell activation/differentiation using a lymphocytic choriomeningitis virus (LCMV) infection mouse model." (PMID 40111008, 2025). "The scTCR‐seq further showed that common T cell clones highly expanded in WT cells after infection were rarely found in the Pdcd5−/− group." (PMID 40111008, 2025).
PDCD5 also shares sentences with these, for which no sentence is quoted: psoriasis (2 papers); anaplastic glioma (1); bladder cancer (1); cardiac diseases (1); cerebral infarction (1); cervical cancer (1); chronic asthma (1); chronic myeloid leukemia (1); colon carcinoma (1); endothelial dysfunction (1); gastrointestinal stromal tumor (1); Hashimoto thyroiditis (1); heart failure (1); ischemic heart disease (1); laryngeal squamous cell carcinoma (1); ovarian serous carcinoma (1); prostate carcinoma (1); renal cell carcinoma (1); renal clear cell carcinomas (1).